INS (insulin)
Diseases named in the same sentence as INS in open-access papers (continued):
Sharing a sentence is not in itself a finding about the gene and the disease.
diabetes (continued). "Different gene mutations can lead to varied pancreatic β-cell functions and insulin sensitivities, thereby affecting the clinical manifestations and treatment needs of diabetes." (PMID 40260393, 2025). "This is an expected result, as the pancreatic insulin reserve gradually decreases during diabetes mellitus treatment, potentially increasing the patient’s insulin requirements." (PMID 41304478, 2025). "From CGM systems and automated insulin delivery technologies to nanomedicine-based solutions and gene therapy, the future of diabetes care is shifting toward precision medicine and curative interventions." (PMID 40217595, 2025). "There is a more extended history of effective treatment options for diabetes, such as insulin, metformin, and newer classes like GLP-1 receptor agonists." (PMID 40771453, 2025). "Diabetes mellitus (DM) is a chronic metabolic disorder characterized by persistent hyperglycemia resulting from defects in insulin secretion and/or insulin inefficiency." (PMID 40869431, 2025). "His medical history included type 2 diabetes mellitus and diabetic peripheral neuropathy, managed with long-term insulin therapy." (PMID 41019039, 2025). "Then, in 1936, Britain’s Sir Harold Himsworth first demonstrated the presence of sensitivity or insensitivity in people with diabetes to exogenous insulin for glucose utilization, introducing the concept known today as insulin resistance." (PMID 39861488, 2025). "This study evaluates the effectiveness of Bluetooth-enabled glucometers (BTG) versus Traditional glucometers (TG) in a telehealth insulin titration program for individuals with diabetes." (PMID 41476921, 2025). "Diabetes is an escalating chronic metabolic disorder globally, primarily characterized by elevated blood glucose levels resulting from inadequate insulin secretion or impaired insulin function." (PMID 40260393, 2025). "We confirmed biomarkers, i.e., a history of high glucose level/diabetes, insulin and cholesterol, which align with the previous studies." (PMID 40082942, 2025). "In terms of diabetes management strategies, the Diabetes Control and Complications Trial (DCCT) notably found that intensive insulin therapy was associated with greater weight gain in participants with type 1 diabetes compared with conventional treatment." (PMID 39933614, 2025). "Especially, CDC42 was reported as a regulator for not only diabetes, but also insulin secretion and development." (PMID 41000275, 2025). "Diabetes arises from insufficient insulin production or impaired insulin function, leading to elevated blood glucose levels." (PMID 40404997, 2025). "Reduced nitric oxide can decrease glucose uptake in skeletal muscles in response to insulin, leading to insulin resistance and diabetes." (PMID 41567799, 2025). "Diabetes education and management strategies should be individualized and include diet and cultural habits for Ramadan, insulin dosing and timing tailored for Ramadan to help T1D patients safely fast, and counseling on after-Ramadan management." (PMID 40510485, 2025). "Cluster 1, including 115 (46%) patients, was characterized by either low insulin secretion (low HOMA-2B index) or resistance (low HOMA2-IR index), and was labeled severe insulin-deficient diabetes (SIDD)." (PMID 41003147, 2025). "Diabetes mellitus is characterized by insufficient insulin secretion or an inadequate response of the body to insulin." (PMID 39927165, 2025). "Fifth, among patients with diabetes, reductions were found in the use of all classes of antidiabetic agents, including insulin." (PMID 40369249, 2025). "The pathophysiology of diabetes stems from a key hormone, insulin, produced by the β-cells in the pancreas, that helps the body utilize available glucose efficiently via the glucose transport-4 receptor (GLUT4)." (PMID 40507585, 2025).
diabetes (continued). "Third, selective knockdown of hepatic Rspo3 exacerbates diabetes and fatty liver change, and then decreases insulin sensitivity in remote organs such as skeletal muscle and adipose tissue as well as in the liver." (PMID 39854351, 2025). "Type 2 DM (T2DM) is a general diabetes category, and it is categorized as hyperglycemia because of insufficient insulin generation in the human body." (PMID 40933380, 2025). "In the subgroup analysis of patients with diabetes, those receiving four daily insulin injections had a longer disease duration and similar HbA1c and fasting glucose levels compared with those on a single basal regimen." (PMID 41304478, 2025). "Disruptions in INS granule formation or maturation—caused by mutations, oxidative stress, or other defects—can lead to granule dysfunction, misfolded INS, and impaired secretion, contributing to β-cell stress and diabetes progression." (PMID 40052150, 2025). "The second theme focused on insulin and knowledge about the management of diabetes with the use of insulin." (PMID 40290070, 2025). "As benefits, it expands knowledge about the disease andfacilitates practical training in essential skills for diabetes care, such as bloodglucose monitoring and insulin administration." (PMID 39899746, 2025). "The impaired β-cell function to reduce glucose-stimulated insulin secretion (GSIS) is a critical pathophysiological event of diabetes." (PMID 40703332, 2025). "Aptamer-based biosensors are also being explored for diabetes management technologies, such as for glucose and insulin detection." (PMID 40422016, 2025). "Effective management strategies often focus on improving insulin sensitivity and enhancing antioxidant defenses to mitigate diabetes-related complications." (PMID 40569910, 2025). "Proper insulin administration is a cornerstone of effective diabetes management, and errors in technique or understanding can compromise glycemic control and long-term health outcomes." (PMID 40471961, 2025). "By improving knowledge and ensuring access to reliable diabetes-related information, insulin usage practices can be improved, leading to better health outcomes for diabetic patients." (PMID 40471961, 2025). "Over time, cellular decompensation and absolute insulin levels decrease, but this usually only occurs in the advanced stages of type 2 diabetes mellitus." (PMID 40989682, 2025). "Mean HbA1c levels across centers calculated from measurements current as of December 31, 2023, analyzed by categories of accessibility of and reimbursement for diabetes technologies and insulin." (PMID 40864470, 2025). "Reductions in BMI, HbA1c, triglycerides and insulin requirements were observed in 14 patients with FPLD who were prescribed tirzepatide for the treatment of diabetes (median treatment period of 9 months)." (PMID 40842493, 2025). "Men with diabetes also exhibit insulin resistance, which leads to an elevation in the serum levels of insulin and insulin-like growth factor-1 (IGF-1), promoting cell proliferation and survival in various cancers, including prostate cancer." (PMID 41367482, 2025). "Many patients in the SP cohort also had diabetes (63.1%); 43.9% of patients in this cohort were taking metformin (vs. 74.8% in the PP cohort) and 47.6% were taking insulin (vs. 41.6% in the PP cohort)." (PMID 40161385, 2025). "Apart from the liver and skeletal muscle, adipose tissue is one of the insulin-sensitive tissues whose function is significantly impaired in diabetes." (PMID 40806520, 2025). "Another study demonstrated that diabetes treatments that involve insulin or insulin secretagogues elevate the likelihood of developing solid tumors." (PMID 40004457, 2025).
diabetes (continued). "Diabetes is a chronic disorder characterized by elevated blood glucose levels resulting from insufficient insulin production or impaired insulin action." (PMID 41257676, 2025). "Adjusted for age, sex, duration of diabetes, presence of hypertension, BMI, eGFR, albuminuria, smoking, insulin treatment, and use of sulfonylurea and aspirin." (PMID 41282290, 2025). "CDS tools using EHR data have been used successfully to reduce hyperglycaemic events and inappropriate insulin use among inpatients with diabetes." (PMID 40480914, 2025). "In the present study, Ficus pumila L. extract, ingested by patients who developed diabetes after COVID-19 infection, stimulated insulin secretion capacity and improved insulin resistance." (PMID 39861420, 2025). "A significantly higher proportion of ISR patients were on insulin therapy (p = 0.01), suggesting more advanced or poorly controlled diabetes in this subgroup." (PMID 40978996, 2025). "Diabetes results from insufficient insulin production by beta cells in the pancreas (Type I diabetes), or resistance/insensitivity to insulin (Type II diabetes), resulting in hyperglycaemia (and/or uncontrolled hypoglycaemia)." (PMID 39973199, 2025). "In the case of obesity, the body produces large amounts of insulin that can lead to a reduction in the function of β cells to produce insulin, further leading to insulin resistance (IR), and high BMI also leads to a high prevalence of pre-diabetes." (PMID 40140819, 2025). "Diabetes is a group of metabolic disorders characterized by hyperglycemia resulting from impairment of insulin secretion, defects in insulin action, or a combination of both." (PMID 41141270, 2025). "In older subjects, abnormalities in both insulin sensitivity and insulin secretion gradually lead to impaired glucose tolerance and consequently to clinically manifest diabetes." (PMID 40724814, 2025). "For instance, understanding patient struggles with diabetes management led to successful automated insulin delivery systems, while concerns about privacy, complexity, and workflow disruption can hinder adoption." (PMID 40499040, 2025). "In diabetes mellitus, chronic low-grade inflammation affects pancreatic islets, liver, and adipose tissue, contributing to impaired insulin secretion and systemic insulin resistance." (PMID 41007869, 2025). "Diabetes mellitus typically arises due to either insufficient insulin secretion resulting from the destruction of β cells or the body’s ineffective utilization of normally produced insulin." (PMID 40649370, 2025). "Women with PCOS often have elevated insulin levels, which can lead to higher blood sugar levels and an increased likelihood of developing diabetes over time." (PMID 40283113, 2025). "A recent study from the Korea National Health and Nutrition Examination Survey indicated a positive correlation among insulin levels, diabetes, and prevalent asthma." (PMID 40922315, 2025). "The integration of glucose sensing and insulin delivery using microneedles is a promising direction, potentially simplifying and optimizing diabetes care." (PMID 39887601, 2025). "Patients with diabetes often suffer from skin damage, tissue irritation, and microcirculatory complications resulting from repeated blood sampling and frequent insulin injections required for glycemic control." (PMID 40863003, 2025). "SHE, CME, and FCME reduce blood glucose levels, plasma insulin levels, insulin resistance, and plasma biomarkers related to diabetes." (PMID 40563879, 2025). "In both the cases we have presented, the use of the DiaPort system improved the QoL and the patients’ attitude toward a more active management of diabetes and insulin therapy." (PMID 40995084, 2025). "Hypoglycemia is a frequent and potentially severe complication that can result in significant brain injury in individuals with diabetes treated with insulin or other hypoglycemic agents and in those undergoing prolonged fasting." (PMID 41408035, 2025).
diabetes (continued). "For patients with advanced diabetes or those who are unable to attain glycemic targets with oral medications, insulin therapy becomes essential." (PMID 40507585, 2025). "Clinical characteristics included a mean diabetes duration of 9.8 years (SD 7.2), insulin therapy in 40.0%, mean body mass index of 24.8 kg/m2 (SD 3.6), and mean Charlson Comorbidity Index of 1.8 (SD 1.9)." (PMID 41048287, 2025). "The American Diabetes Association (ADA) and the American College of Obstetricians and Gynecologists (ACOG) both advise insulin as the first-line medication for GDM." (PMID 40868219, 2025). "This decreased INS output can contribute to hyperglycemia, which ultimately results in the development of diabetes and other metabolic complications." (PMID 40052150, 2025). "Diabetes can contribute to the onset of endometrial cancer through elevated insulin and insulin-like growth factor (IGF) levels, stimulating endometrial cell growth and hormonal imbalances." (PMID 40558241, 2025). "Both bedtime NPH insulin and incretin-based therapy with dipeptidyl peptidase 4 (DPP4) inhibitors are recommended by the American Diabetes Association for use in selected populations, particularly in older adults and individuals in low-resource settings." (PMID 41282288, 2025). "Special attention should be paid to those treated with insulin, the youngest ones, those with pervious diabetes foot ulcer, and those with a history of mental anxiety and/or depression." (PMID 39972441, 2025). "The two main types are Type-1 diabetes mellitus (T1DM), caused by autoimmune destruction of pancreatic beta cells, and Type-2 diabetes mellitus (T2DM), the more common form resulting from insulin resistance in tissues like the liver and muscles." (PMID 40871536, 2025). "This case report describes a 58-year-old woman with type 1 diabetes mellitus who developed considerable abdominal wall lipoatrophy 4 months after initiating insulin pump therapy." (PMID 40746499, 2025). "There are many examples of peptide drugs; insulin, for example, is the first commercial peptide drug and has been thoroughly used to treat diabetes for many years." (PMID 40872537, 2025). "This provided a lower glycemic variability compared to insulin glargine, however diabetes patients sometimes can still require twice daily doses of daily basal insulin for glycemic control." (PMID 40156735, 2025). "Insulin resistance (IR), a hallmark of type 2 diabetes mellitus (T2DM), involves impaired cellular responses to insulin in key metabolic tissues such as skeletal muscle, liver, and adipose tissue." (PMID 40426647, 2025). "Beyond the pancreas, physiological overexpression of SIRT6 enhances insulin sensitivity in skeletal muscle and liver, providing protection against type 2 diabetes mellitus." (PMID 41304967, 2025). "Therapeutic proteins, such as insulin, growth factors, and clotting factors, have been pivotal in the treatment of diseases like diabetes, hemophilia, and growth disorders." (PMID 41586190, 2025). "This cross-sectional study collated data regarding the accessibility and reimbursement of diabetes technologies and insulin from 81 centers across 56 countries, inclusive of 42 349 children with T1D." (PMID 40864470, 2025). "This study aims to explore the effects of liver transplantation on insulin and oral anti‐glycaemic agents' requirements in patients with pre‐existing diabetes." (PMID 40664615, 2025). "PTEN acts directly on insulin signaling active in both breast cancer and type 2 diabetes mellitus via the PI3K/Akt pathway." (PMID 40989682, 2025). "Diabetes mellitus constitutes a chronic metabolic disorder characterized by the body’s failure to produce sufficient insulin, inability to effectively utilize insulin, or a combination of both conditions." (PMID 41464992, 2025). "Estimated glucose disposal rate (eGDR) was a novel non-insulin-based marker of insulin resistance (IR), which had been used in many studies to evaluate the clinical prognosis of diabetes." (PMID 40756509, 2025).
diabetes (continued). "Misfolding can affect the synthesis, secretion, and function of INS, which in turn can aggravate diabetes." (PMID 40052150, 2025). "He had only accepted self-injected long-acting insulin treatment for diabetes mellitus (DM) (4 units per day)." (PMID 40084265, 2025). "For people with diabetes who are treated with insulin, the interventional focus shifts from a simple tablet intake (oral antidiabetics) to insulin application requiring stronger self-management skills." (PMID 40661654, 2025). "Elevated serum levels of TC and TG (key indicators of diabetes progression) are primarily attributed to impaired insulin regulation." (PMID 41376068, 2025). "The system has been widely used in the percutaneous delivery of oligonucleotides, vaccines, growth factors, insulin, etc., and has been applied in the treatment of tumors, tissue repair, skin diseases, and diabetes." (PMID 39887601, 2025). "Diabetes mellitus (DM) is characterized by chronic hyperglycemia resulting from defects in insulin secretion, insulin action, or both." (PMID 40305215, 2025). "Type 2 diabetes is characterised by dysfunction of pancreatic islet cells and consequent disturbances in insulin synthesis and secretion, and by insulin resistance in the peripheral tissues, resulting in impaired glucose metabolism or overt diabetes." (PMID 39621103, 2025). "Zinc (Zn) cations came under focus as a possible antidiabetic agent in 1980, when ZnCl2 was reported to stimulate lipogenesis in rat adipocytes in a manner similar to the action of insulin, aiding both types of diabetes treatment under high doses of ZnCl2." (PMID 40286074, 2025). "We delved into the alterations in m6A modification sites following intensive insulin therapy in diabetes mellitus utilizing MeRIP-seq, RNA-seq, and in vitro cellular experiments." (PMID 40299682, 2025). "The incidence of diabetes also increases gradually during puberty, and it is more prevalent in women, possibly due to hormonal variations and insulin resistance." (PMID 39946391, 2025). "Diabetes mellitus (DM) is a metabolic disorder characterized by a chronic high blood glucose level related to insulin resistance and insufficient insulin production." (PMID 40077549, 2025). "In diabetes mellitus, inflammation occurs not only in pancreatic islets but also in adipose tissue and the liver, where it drives systemic insulin resistance." (PMID 41007869, 2025). "Conversely, OSA exacerbates diabetes via mechanisms including nocturnal hypoxemia, systemic inflammation, insulin resistance, and increased sympathetic activity." (PMID 41007822, 2025). "The antidiabetic and insulin nanocarriers employed for the management of diabetes mellitus comprise various types of nanoparticles and self-nanoemulsifying antidiabetic drug delivery systems." (PMID 41463606, 2025). "Hydrogels show promise in treating metabolic diseases, particularly diabetes and metabolic syndrome, through various approaches, including glucose-responsive insulin delivery systems, which release insulin in response to high blood sugar." (PMID 41294602, 2025). "IL-9 has been shown to promote IL-5 and IL-13 signaling, which have already been demonstrated to improve insulin sensitivity during diabetes." (PMID 40962954, 2025). "Type 2 diabetes mellitus (T2DM) is mainly due to the failure of tissues to respond to insulin or synthesize enough insulin." (PMID 41302106, 2025). "Diabetes mellitus, commonly known as diabetes, is a chronic metabolic disease characterized by insufficient insulin production by the pancreas (Type 1 diabetes) or ineffective utilization of the produced insulin by the body (Type 2 diabetes)." (PMID 40309033, 2025). "Two subthemes addressing the intersectionality of glucose and insulin management, food, diabetes management devices and technology were identified." (PMID 41358572, 2025).